TCIRG1 (T cell immune regulator 1, ATPase H+ transporting V0 subunit a3)
Diseases named in the same sentence as TCIRG1 in open-access papers (continued):
Sharing a sentence is not in itself a finding about the gene and the disease.
tumor (11 papers, 2019 to 2025). "In our study, we found that aberrant ASE of TCIRG1 was associated with poor prognosis and tumor metastasis in patients with KIRC." (PMID 31681747, 2019). "In addition, higher Immune and Estimate Scores and lower Tumor Purity were associated with poorer OS in ccRCC patients, suggesting that the expression of TCIRG1 may be associated with changes in the TME during the diagnosis and prognosis of ccRCC." (PMID 37649034, 2023). "High TCIRG1-expressing KIRC patients may incur a greater risk of tumor progression, and by the diversity of immune cell infiltration levels and status between the high- and low-TCIRG1 expression subgroups, patients with high TCIRG1 expression may receive a more precise immunotherapeutic strategy." (PMID 36230507, 2022). "Transwell assays and subcutaneous tumor formation experiments in nude mice demonstrated that tumor tissues with high TCIRG1 expression exhibited stronger invasiveness." (PMID 41180155, 2025). "Using CIBERSORT and quanTIseq, the fraction of tumor-infiltrating immune cells (TIICs) was segmented in the TCGA cohort to further examine the link between TCIRG1 and immune cells in ccRCC tissue." (PMID 36230507, 2022). "To explore the role of TCIRG1 in the progression of ccRCC, we explored the relationship between the clinicopathological stage of the tumor and the prognostic value of TCIRG1 expression." (PMID 36230507, 2022). "The up-regulated CEP55, IFI44, NCF4, and TCIRG1 with HR > 1 were regarded as oncogenes and were proved to be closely related to tumor progression by using comprehensive bioinformatics analysis." (PMID 33101364, 2020). "With regard to tumor metastasis, TCIRG1 was reported to modulate the EMT regulatory proteins, such as E-cadherin, N-cadherin, Fibronectin, Vimentin, Snail and Slug, and regulate tumor invasion and metastasis in MDA-MB-231, B16-F10, and SNU475 cells." (PMID 31681747, 2019). "In the database of UALCAN and LinkedOmics, RHOT2, and TCIRG1 were up-regulated in tumor than normal tissue and associated with tumor stage and OS significantly." (PMID 31681747, 2019). "Further in vivo studies are necessary to validate TCIRG1's tumor-promoting effects." (PMID 41180155, 2025). "TCIRG1, a gene crucial for cellular life functions through its acidification dependency, acts as a promoter for tumor growth by influencing aerobic glycolysis and the tumor immune microenvironment in KIRC." (PMID 38730293, 2024). "TCIRG1 expression varied drastically depending on the clinical stage of the tumor." (PMID 36230507, 2022). "Additionally, TCIRG1 expression was downregulated in 20 tumor tissues, including ACC, BRAC, CESC, and COAD." (PMID 36230507, 2022). "Therefore, we used the ESTIMATE algorithm to calculate Stromal Score, Tumor Purity, Immune Score, and Estimate Score in ccRCC tissue based on the TCGA transcriptome data, and found that they had a significant correlation with TCIRG1 expression." (PMID 37649034, 2023). "Our results demonstrate that the glycolysis-related biomarker TCIRG1 is a tumor-promoting factor by affecting aerobic glycolysis and tumor immune microenvironment in ccRCC, and this finding may provide a new idea for the treatment of ccRCC by combination of metabolic intervention and immunotherapy." (PMID 37649034, 2023). "Finally, we explored the effect of TCIRG1 knockdown on tumor cells." (PMID 36230507, 2022). "Next, we explored the expression of TCIRG1 in different normal and tumor tissues using the TIMER 2.0 database, and found the expression of TCIRG1 in renal tumor tissues was higher than that in normal renal tissues." (PMID 37649034, 2023). "The results demonstrated that NOS3 and TCIRG1 were highly expressed in tumor cells and samples compared to normal cells and tissues, while GPX3 and DUSP1 were expressed at low levels in tumor cells and samples." (PMID 37124616, 2023).
tumor (continued). "Oxidative phosphorylation components (NDFs, COXs, TCIRG1, LHPP) and chemical carcinogenesis pathways involving reactive oxygen species (CYP1B1, GSTs, AKT2, IKBKB, MAPK3, MAP2K2) exacerbate DNA damage and promote tumour aggressiveness." (PMID 41007296, 2025). "Finally, LightGBM and XGBoost algorithms identified TCIRG1 as a key model feature and a novel biomarker in KIRC for experimental characterization using western blot, immunohistochemistry, multiple immunofluorescence (mIHC), subcutaneous tumor formation in nude mice, and Transwell assays." (PMID 41180155, 2025). "Using qRT-PCR for analysis, the expression of TCIRG1 showed clear differences in the pCR and partial response (PR) cases of the NICT group, and it was also related to changes in the tumor size of the NONE and NCT groups." (PMID 39076970, 2024).
bone disorder (2 papers, 2023 to 2025). "One patient carried a likely pathogenic variant in TCIRG1 among patients not suspected of monogenic bone disorders (2%)." (PMID 37076969, 2023). "Eight AFF patients (NS2‐9) without a clinical suspicion of a monogenic bone disorder carried one or more heterozygous VUS with a CADD score ≥ 20 in P4HB, PHEX, TNFRSF11A, CREB3L1, TCIRG1, SERPINH1, LEPRE1, and PLOD2." (PMID 37076969, 2023).
neurodegenerative disease (1 paper, 2018). A disorder of the central nervous system characterized by gradual and progressive loss of neural tissue and neurologic function. "Oxidative phosphorylation genes specific for HCHWA-D, i.e., not represented in the other neurodegenerative disease categories were the ATP6V subunits, COX14, COX15, LRPPRC, and TCIRG1." (PMID 29706885, 2018).
TCIRG1 also shares sentences with these, for which no sentence is quoted: Hypocalcemia (3 papers); melanoma (3); COVID-19 (2); infection (2); neurological diseases (2); osteoarthritis (2); osteoporosis (2); acute graft versus host disease (1); adenosquamous carcinoma (1); anemia (1); autoimmune disease (1); autosomal dominant osteopetrosis (1); autosomal dominant osteopetrosis type 2 (1); Autosomal recessive malignant osteopetrosis (1); bacterial infection (1); bladder cancer (1); bone marrow failure (1); brain glioma (1); breast tumors (1); cholangiocarcinoma (1); cholestasis (1); cutis laxa (1); cystic fibrosis (1); deafness (1); esophageal adenocarcinoma (1); gastric cancer (1); genetic disorder (1); hematological disorders (1); hypersplenism (1); hypotrichosis (1).
A further 18 diseases each share a sentence with TCIRG1 in 1 paper.